CRP (C-reactive protein)
Diseases named in the same sentence as CRP in open-access papers (continued):
Sharing a sentence is not in itself a finding about the gene and the disease.
Cognitive impairment (continued). "Similarly, a geriatric cross-sectional study from China showed increased CRP was associated with cognitive impairment." (PMID 37190623, 2023). "Measurement of key biological processes implicated in mood disorder aetiology and cognitive impairment will occur in this trial, including assessing levels of inflammatory markers (pro-inflammatory cytokines and C-Reactive Protein; CRP), vitamin C, and androgens (females only)." (PMID 35164720, 2022). "In studies of BD, elevated levels of CRP inflammation may be associated with a broad range of cognitive deficits in patients, and researches have also identified CRP as a significant positive predictor of proxy cognitive decline." (PMID 36406755, 2022). "Associations of the combined effect of CRP and HbA1c with mild cognitive impairment (MCI)a." (PMID 35252292, 2022). "The variables independently associated with cognitive impairment were the mean CRP along the follow-up (OR [IC 95%], 1.291 [1.002-1.663]; p=0.047), depression (OR [IC 95%], 1.178 [1.001-386]; p=0.049) and biological treatment (OR [IC 95%], 0.196 [0.039-0.978]; p=0.049)." (PMID 36096831, 2022). "The multivariate regression analysis revealed that a low preoperative MOCA score and severe postoperative pain were independent risk factors for mild and severe cognitive impairment, while a high postoperative CRP level was only an independent risk factor for mild cognitive impairment." (PMID 35224095, 2022). "Second, different nocturnal and daytime sleep patterns might affect the sleep-inflammation processes (e.g., elevated CRP level), which has been suggested to be associated with the cognitive impairment." (PMID 34091444, 2021). "In addition to being a risk factor of cardiovascular disease, elevated levels of high-sensitivity C-reactive protein (hs-CRP) are suggested to serve as a biomarker for cognitive impairment risk associated with systemic inflammation." (PMID 34680464, 2021). "A number of studies suggest that CRP might be associated with cognitive impairment, with some evidence of increased risk of cognitive decline." (PMID 33382815, 2020). "CRP levels were associated with cognitive impairment in both inpatient and outpatient samples." (PMID 32994460, 2020). "Moreover, increased levels of inflammatory markers such as C-reactive protein and proinflammatory interleukins are also common and have been implicated in frailty, cognitive impairment, and AD." (PMID 30200236, 2018). "Increased CRP has been recently associated with cognitive impairment in SZ, which suggests that anti-inflammatory strategies may improve the debilitating course of this illness." (PMID 30190688, 2018). "High CRP levels were also predictive of increased susceptibility to cognitive impairment." (PMID 27259001, 2017). "A long-term study (over 20 years) indicated that repeated high or increasing IL-6 was associated with cognitive impairment; CRP alterations were inconsistent with cognition, which may involve impacts of statin medications and survival effects." (PMID 26682220, 2015). "Certain risk factors for cognitive impairment appear modifiable, and CRP represents a potentially modifiable inflammation marker that may be associated with an increased risk of cognitive impairment." (PMID 24587705, 2014). "There are some pieces of evidence that elevated serum CRP levels may be a useful biomarker to identify individuals at an increased risk for cognitive impairment." (PMID 24587705, 2014). "Nevertheless, increased CRP levels may cause cognitive impairment." (PMID 35054785, 2022). "Moreover, other population-based studies have demonstrated that dietary levels of fruit intake and vitamin C are inversely related to levels of C reactive protein (CRP), an inflammatory marker associated with age-related chronic diseases, cognitive impairment, and frailty." (PMID 34025388, 2021).
Cognitive impairment (continued). "In addition, an increase in CRP over time has been associated with cognitive decline in two studies, so longitudinal measurement may further help clarify the role of CRP on risk of cognitive impairment." (PMID 33382815, 2020). "Likewise, heightened levels of C-reactive protein (CRP) have been associated cross sectionally with mild cognitive impairment and there is some evidence for a longitudinal effect, with both CRP and interleukin (IL)-6 being associated with worsening of cognitive function in some population studies." (PMID 26865259, 2016). "CRP levels exceeding 4.3 mg/L predicted global cognitive impairment with a sensitivity of 72.41% and specificity of 73.63%." (PMID 41367212, 2025). "Meanwhile, the expression levels of CRP in patients with cognitive impairment and dementia are closely related to cognitive decline." (PMID 40852521, 2025). "It is unclear if high CRP levels affect the link between poor sleep and cognitive impairment in MDD." (PMID 40673224, 2025). "The presence of MCR suggests existing cognitive impairment and possibly compromised brain functions, while a high CRP serum level indicates systemic inflammation." (PMID 39913250, 2025). "CRP, a systemic inflammatory marker, not only reflects acute-phase responses but also predicts long-term cognitive deficits in TBI." (PMID 40443507, 2025). "This can confound the relationship between CRP and major neurocognitive disorder, making it difficult to determine if elevated CRP is specifically related to cognitive impairment." (PMID 39913250, 2025). "C‐reactive protein (CRP) levels at diagnosis have been shown to predict both subjective and objective long‐term cognitive impairment." (PMID 40772479, 2025). "Even after adjusting for age, comorbidity burden (CCI), DLCO%, and CRP, having an ILD diagnosis is significantly associated with increased odds of cognitive impairment (OR = 2.72, 95% CI 1.14–6.48, p = 0.024)." (PMID 41515499, 2025). "Cognitive impairments in bipolar disorder patients can be classified into distinct subgroups, which are associated with serum levels of BDNF and CRP." (PMID 41367212, 2025). "Preliminary studies showing CRP mediating the liver–brain axis have been reported, especially with CRP in liver fibrosis and cognitive impairment." (PMID 38672162, 2024). "The IBI obtained by adding CRP to the neutrophil/lymphocyte ratio showed strong correlations with the severity of cognitive impairment in our study." (PMID 39398776, 2024). "Participants with both vitamin D deficiency and high hs-CRP were more likely to be older, illiterate, ADL impaired, cognitive impaired, had lower albumin, and had higher fasting blood glucose." (PMID 38302956, 2024). "This study aimed to evaluate the associations of baseline high-sensitivity C-reactive protein (Hs-CRP) and its change with subsequent cognitive decline and cognitive impairment." (PMID 37190623, 2023). "In other words, individuals with high D-dimer relative to CRP tend to have subjective cognitive deficits, as well as signs of occupational impact, at 6 and 12 months." (PMID 37653345, 2023). "A second dimension links high D-dimer (relative to CRP) to subjective cognitive deficits, as well as occupational impact at 6 and 12 months after infection." (PMID 37653345, 2023). "A first profile links elevated fibrinogen relative to C-reactive protein with both objective and subjective cognitive deficits." (PMID 37653345, 2023). "A first dimension links high fibrinogen (relative to CRP) to objective and subjective cognitive deficits 6 and 12 months after infection." (PMID 37653345, 2023). "In the same way that IL-6 is altered in patients with cognitive impairment, a recent review found that CRP is also involved in this mechanism." (PMID 37251808, 2023). "A second profile links elevated D-dimer relative to C-reactive protein with subjective cognitive deficits and occupational impact." (PMID 37653345, 2023).
Cognitive impairment (continued). "The researches of IL-1β and CRP of cognitive impairment in psychiatric disorders is still controversial." (PMID 36406755, 2022). "Future studies should focus on the clinical implementation of hs-CRP or HbA1c to monitor cognitive deficits." (PMID 35172860, 2022). "We already mentioned a cross-sectional study evaluating the correlation of CRP with depressive symptoms and cognitive impairment in 149 MDD patients treated with fluoxetine or venlafaxine for six weeks." (PMID 35163538, 2022). "Nevertheless, our study demonstrated that the levels of some proteins, including TC, LDL-C, Hcy, and CRP, remarkably changed in patients with post-stroke cognitive impairment." (PMID 35054785, 2022). "Advanced age, higher levels of WBC, neutrophil, CRP or creatinine, the presence of malignancy, cognitive impairment, and complications were strongly correlated with hastening death." (PMID 33805755, 2021). "A meta-analysis found that the reduced brain-derived neurotrophic factor (BDNF) levels and elevated C-reactive protein (CRP) in SCZ had a significant relationship with cognitive impairment, particularly in subjects with chronic SCZ." (PMID 34354618, 2021). "The most important were advanced age, the presence of malignancy, a higher Charlson Index, WBC (1000/μL increase), CRP (100 mg/L increase), the presence of complications, and the presence of cognitive impairment." (PMID 33805755, 2021). "In our multicentre study, the independent risk factors for mortality at day 90 were older age, inadequate CDI therapy, cachexia, malignancy, Charlson Index, LTC facility care, elevated WBC, elevated CRP, bacteraemia, complications, and cognitive impairment." (PMID 33805755, 2021). "Multivariable logistic regression was used to estimate the interactions of hs-CRP levels with body mass index (BMI) on the effects of cognitive impairment and its subtypes." (PMID 33363509, 2020). "In one of the few studies analyzing altitude, inflammation and cognition, it was possible to verify a correlation between the increase in CRP levels and cognitive impairment." (PMID 33255790, 2020). "Multivariate-adjusted odd ratios (OR) for cognitive impairment sub-items according to hs-CRP levels and BMI." (PMID 33363509, 2020). "Our sensitivity analyses, additionally adjusting for ethnic group, frequent milk intake, cognitive impairment, and high sensitivity c-reactive protein, yielded results largely similar to the primary results." (PMID 30987591, 2019). "Due to low number of studies, it is difficult to draw conclusions on the involvement of CRP and cytokine alterations in the development of cognitive deficits in bipolar disorder." (PMID 30349492, 2018). "Multiple studies have demonstrated an association between elevated CRP levels post-TBI and ongoing psychological dysfunction and cognitive impairment." (PMID 28355230, 2017). "C-reactive protein (CRP), a marker of inflammation is implicated in mood disorders, cognitive disorders and AD, and Post-Traumatic Stress Disorder (PTSD)." (PMID 29302258, 2017). "Thus, whilst elevated CRP has been associated with greater cognitive impairment in some non-psychiatric samples, the association appears to be restricted to populations in which cognitive impairment is also prevalent (e.g., older adults and those with physical health conditions)." (PMID 28694011, 2017). "In February 2011, a third relapse—with cognitive impairment, raised CRP blood level at 53 mg/L, and new ischemic lesions on cranial MRI—occurred under 30 mg/day of prednisone." (PMID 25526454, 2014). "CRP levels between patients with cognitive impairment were significantly higher (5.82 ± 3.21) than among controls (4.33 ± 2.02; P: 0.002)." (PMID 24587705, 2014). "CRP levels in patients with cognitive impairment were significantly higher (5.82 ± 3.21) than among controls (4.33 ± 2.02; P: 0.002)." (PMID 24587705, 2014).
Cognitive impairment (continued). "Adjusted logistic regression analysis revealed that people with high levels of CRP had 2.9 (95% CI: 1.26–6.44) higher chance to present cognitive impairment." (PMID 24587705, 2014). "Longitudinal studies would expect to find steeper rates of neural and cognitive impairment in people carrying higher levels of proinflammatory proteins, like CRP." (PMID 24587705, 2014). "Thereby, our findings are in line with other studies that found that elevated CRP levels are related to cognitive impairment." (PMID 24587705, 2014). "The purpose of this study is to assess the relationship between serum levels of CRP, the presence of leukoaraiosis, and cognitive impairment in a population of coronary patients over 50 years old." (PMID 24587705, 2014). "Patients with CRP levels ≥5.0 had 2.9 (95% CI: 1.26–6.44) times more chance to present cognitive impairment (P: 0.012)." (PMID 24587705, 2014). "Patients with CRP levels ≥5.0 had 2.9 (95% CI: 1.26–6.44) times more chance to present cognitive impairment (P: 0.012) than controls." (PMID 24587705, 2014). "In this study, CRP levels are higher among patients with cognitive deficits and individuals with CRP levels ≥5.0 had 2.9 (95% CI: 1.26–6.44) times more chance to present cognitive impairment (P: 0.012)." (PMID 24587705, 2014). "The median serum CRP in our cognitive impairment group was 2.08 mg/L, much higher than in the control sample (0.21 mg/L)." (PMID 23978069, 2013). "Plasma concentrations of C-reactive protein (CRP), a marker of chronic inflammation, have been associated with cognitive impairment in old age." (PMID 21915265, 2011). "Hence, it can be inferred that an increase in CRP concentration is a critical indicator to predict cognitive disorder." (PMID 40966684, 2025). "We hypothesize that improving sleep quality may potentially facilitate a reduction in the body’s inflammatory response, while improvement in CRP levels could ameliorate cognitive impairment resulting from poor sleep quality." (PMID 40673224, 2025). "After targeted therapy, the CRP concentration (mean 10.64, SD 15.37 mg/L) in the group with no cognitive disorder was also significantly lower than that of the group with cognitive disorder (mean 20.09, SD 27.37 mg/L), and there was a significant difference between the 2 groups (z=−1.975; P=.048)." (PMID 40966684, 2025). "The correlation between CRP levels and sleep/cognitive indicators implies that routine CRP screening in MDD patients could potentially serve as a valuable tool to identify early cognitive impairment." (PMID 40673224, 2025). "Consistent with our findings, MDD with lower SE correlates with higher CRP levels, which may be related to the severity of cognitive impairment." (PMID 40673224, 2025). "CRP is also considered a marker of inflammation involved in the pathophysiology of CSVD, closely related to larger WMH volume, PVS, brain atrophy, and deep CMBs, and is thus significantly associated with greater cognitive impairments in patients with CSVD." (PMID 40376151, 2025). "Further analysis revealed a negative correlation between CRP levels and performance across all neurocognitive domains, suggesting that higher inflammation levels were associated with greater cognitive deficits." (PMID 41367212, 2025). "By examining these biomarkers within well-defined cognitive subgroups, we aim to determine whether BDNF and CRP levels can serve as potential indicators of cognitive impairment severity or subgroup classification." (PMID 41367212, 2025). "Recently, elevated CRP levels have been shown to mediate cognitive impairment." (PMID 38672162, 2024). "Increased CRP concentrations may relate to emotional disturbances and cognitive impairments, but the mechanisms remain unclear." (PMID 39554848, 2024). "The association of BPD with elevated levels of homocysteine (Hcy) and high-sensitivity C-reactive protein (hs-CRP) suggests that these inflammatory markers may contribute to cognitive impairment." (PMID 39596351, 2024).
Cognitive impairment (continued). "Surprisingly, it has been determined that, in PD patients with elevated CRP levels, slower progression of cognitive disorders might be expected." (PMID 38392998, 2024). "Older diabetic individuals with mild cognitive impairment may experience depressive symptoms if there are high levels of C-reactive protein (CRP) and adhesion molecules in their blood." (PMID 38892791, 2024). "Furthermore, the current studies suggest that CRP contributes to cognitive impairment at least through two mechanisms." (PMID 37509012, 2023). "Specifically, an increased concentration of CRP may activate microglia, leading to a neurotrophic effect on the brain and cognition in patients with cognitive impairments." (PMID 37593375, 2023). "Baseline Hs-CRP was linearly associated with risk of cognitive impairment, with a positive and monotonic association (p for non-linear trend = 0.059)." (PMID 37190623, 2023). "There was a non-linear association of Hs-CRP change with cognitive impairment (p for non-linear trend = 0.005), and the risk of cognitive impairment had a small decreasing trend until zero and then started to increase rapidly afterwards." (PMID 37190623, 2023). "A first dimension links raised fibrinogen relative to CRP with both objective and subjective cognitive deficits and might reflect immunothrombotic events with potential direct effects of fibrinogen on the brain." (PMID 37653345, 2023). "Therefore, we have reasons to believe that increased CRP level is closely related to cognitive impairment in COPD patients." (PMID 36325191, 2022). "Dexmedetomidine could reduce the incidence of cognitive impairment after intestinal I/R injury, which may be related to decreased levels of inflammatory cytokines IL-1β, IL-6, C-reactive protein, and TNF-α." (PMID 35945306, 2022). "Blood studies showed that higher levels of pro-inflammatory markers were linked with a more severe motor phenotype (IFN-γ, TNF-α, IL-2, and IL-10), faster motor progression (CRP and IL-6), cognitive impairment (IFN-γ, TNF-α, IL-2, and IL-10), and worse sleep quality (CRP)." (PMID 36337703, 2022). "Meanwhile, a study showed that people with cognitive impairment had higher levels of CRP." (PMID 36091504, 2022). "Ten studies analyzed c-reactive protein (CRP), and eight studies measured d-dimer levels; however, only a few studies specifically correlated the levels of these biomarkers to the presence of cognitive deficits, and the results were sparse and inconsistent." (PMID 36556290, 2022). "In addition, older age, higher levels of WBC, neutrophil, CRP or creatinine, the presence of malignancy, cognitive impairment, and complications were strongly correlated with shortening the time from CDI diagnosis to death." (PMID 33805755, 2021). "Similarly, another recent study examined the polygenic overlap between cognitive impairment and plasma CRP and lipids." (PMID 32152295, 2020). "Multivariable adjusted odd ratios (OR) for cognitive impairment according to hs-CRP levels and BMI." (PMID 33363509, 2020). "At the functional level, studies are needed to correlate ceramide and estrogen levels to a broad panel of biomarkers (e.g., lipoprotein profile, C-reactive protein) and clinical outcome measures (e.g., future adverse cardiovascular events and cognitive impairment)." (PMID 30620722, 2019). "This work supports the role of inflammation in psychotic illnesses and suggests that use of peripheral markers (e.g., CRP) in conjunction with diagnosis could be used to identify patients with more cortical neuropathology and cognitive deficits." (PMID 30364161, 2018). "Going beyond previous work, the present study took a novel methodological approach by examining the mediation of systemic inflammation (i.e., serum levels of IL-6, TNF-α and CRP) on age-related cognitive impairments (i.e., deficits in processing speed and short-term memory)." (PMID 30127734, 2018).